PTH (parathyroid hormone)
Diseases named in the same sentence as PTH in open-access papers (continued):
Sharing a sentence is not in itself a finding about the gene and the disease.
vitamin D deficiency (continued). "A total of 80.6% of cases compared to 5.6% of controls had vitamin D deficiency, and 72.2% of cases compared to 2.8% of controls had PTH deficit, both of which showed statistically significant differences (p<0.001)." (PMID 39233987, 2024). "Consistently, the prevalence of severe vitamin D deficiency was higher in vegans compared to the other two groups, and this group presented higher levels of the bone resorption marker NTx and higher PTH levels compared to omnivores." (PMID 39408619, 2024). "Further observation of the study population revealed that the subjects had vitamin D deficiency or high baseline serum PTH levels." (PMID 38160221, 2024). "PTH level was higher in children with vitamin D deficiency as compared with those with vitamin D sufficiency (P = .015)." (PMID 38523666, 2024). "Although this is seen in many cases, not all Vit D deficient individuals manifest with increased PTH levels, and about 10% of diabetic patients with severe vitamin D deficiency have a low PTH." (PMID 39449502, 2024). "The median PTH values were significantly higher among patients with vitamin D deficiency (62.8 ± 31.9 pg/mL vs. 47 ± 22.8 pg/mL, respectively; p < 0.01)." (PMID 38674789, 2024). "In patients with CKD-induced SHPT, VDRAs mitigate the effects of vitamin D deficiency by binding to vitamin D receptors (VDRs) and inhibiting PTH synthesis through gene transcription regulation." (PMID 39208984, 2024). "Our patient was initially advised to limit sun exposure and calcium intake; however, months later, he was found to have vitamin D deficiency (25-hydroxycholecalciferol level of 19.80 ng/mL and PTH level of 72.9 pg/mL)." (PMID 39051296, 2024). "Another notable finding of our study is the prevalence of high PTH levels in patients with vitamin D deficiency." (PMID 38674789, 2024). "The participants who had PTH levels above the median had higher risk of vitamin D deficiency (RR: 1.3; 95%CI: 0.4–2.1)." (PMID 38674904, 2024). "The evaluation indicated severe vitamin D deficiency (25-hydroxy vitamin D 3.0 ng/mL (7.5 nmol/L); reference: >30 ng/mL (>75 nmol/L)) and elevated serum PTH (394 pg/mL (41.8 pmol/L))." (PMID 39478762, 2024). "The Endocrine Society categorizes <20 ng/mL of serum 25(OH)D as vitamin D deficiency, which is accompanied by a persistent increase of parathyroid hormone (PTH) and a reduction in intestinal calcium absorption." (PMID 39583540, 2024). "In retrospect, the exceedingly high initial PTH levels were likely influenced by associated long-standing severe vitamin D deficiency." (PMID 39478762, 2024). "It is possible that vitamin D deficiency, leading to high levels of PTH can negatively influence the metabolism of lipids." (PMID 38412162, 2024). "In this study, we describe MSIA, specially tailored for detecting PTH proteoforms, and assess additional microheterogeneity in PTH related to vitamin D deficiency among patients with diabetes mellitus." (PMID 39449502, 2024). "In general, high preoperative PTH, larger adenomas, and vitamin D deficiency are considered to be the risk factors for persistently elevated PTH after parathyroidectomy." (PMID 39444450, 2024). "While 74.4% of our patients had vitamin D deficiency, 67.2% of them had normal PTH levels and only 31% had a high PTH." (PMID 38982537, 2024). "The children with vitamin D deficiency had significantly higher PTH levels and lower serum calcium levels compared with those who did not (p < 0.001 and p = 0.009, respectively)." (PMID 36986058, 2023). "A total of 11% of patients had elevated parathyroid hormone, suggesting disordered calcium homeostasis, and these were all associated with vitamin D deficiency." (PMID 37375707, 2023). "His laboratory tests showed highly elevated gastrin and chromogranin A levels during proton pump inhibitor (PPI) and famotidine treatment, elevated PTH level, normocalcemia, and normophosphatemia with vitamin D deficiency." (PMID 37008936, 2023).
vitamin D deficiency (continued). "This study aimed to investigate the relations between vitamin D deficiency with thyroid and parathyroid hormone in the first trimester of pregnancy at the main general clinical centers in Gaza city and North Gaza, Palestine, during April 2019 –April 2020." (PMID 36996084, 2023). "One child had secondary hyperparathyroidism associated with a profound vitamin D deficiency [PTH: 159.8 pg/ml; 25(OH)D: 20 nmol/L]." (PMID 38094189, 2023). "Another mechanism linked to bone loss in Tenofovir users is vitamin D deficiency, which causes an increase in the serum concentration of PTH, and consequently, bone remodeling, leading to a reduction in bone density." (PMID 37159593, 2023). "A 25(OH)D3 level below 50 nmol/L is considered as D-vitamin deficiency based on the observation that lower values are associated with increased levels of parathyroid hormone." (PMID 38084202, 2023). "In vitamin D deficiency, there is an elevation of PTH and, consequently, an increase in renal tubular reabsorption of calcium and its mobilization from the bone through osteoclastic stimulation." (PMID 36771474, 2023). "The cut-off value of vitamin D deficiency was defined as the circulating 25(OH)D levels at which serum PTH is maximally suppressed or rapidly raised." (PMID 36721726, 2023). "By evaluating the relationship between 25(OH)D and PTH, we calculated a 25(OH)D threshold of ≥ 55 nmol/L for vitamin D sufficiency and a 25(OH)D threshold of < 22 nmol/L for vitamin D deficiency." (PMID 36920734, 2023). "Considering the cut-off value of circulating 25(OH)D ≤12⋅48 ng/ml as vitamin D deficiency based on the best fit model for PTH/25(OH)D relation in our data, 45 (20 %) women were considered to be vitamin D-deficient." (PMID 36721726, 2023). "According to FP1 analysis, the vitamin D deficiency cut-point for the classical endocrine function using serum PTH as a marker was the 25(OH)D threshold of 12·48 ng/ml, at which serum PTH quickly rose." (PMID 36721726, 2023). "Although parathyroid hormone (PTH) levels are known to be increased in PHPT patients with vitamin D deficiency (<20 ng/ml), the underlying pathophysiological basis for this relationship remains poorly understood." (PMID 36992820, 2023). "This study reported 25(OH)D thresholds of vitamin D sufficiency at 55 nmol/L and vitamin D deficiency at 22 nmol/L, and consequently established PTH RIs in subjects with sufficient vitamin D for northern China population for the first time." (PMID 36920734, 2023). "At the time of the visit, 58 (77%) patients had vitamin D deficiency and 44% (n=34) had increased level of parathyroid hormone." (PMID 37766687, 2023). "Despite the high rates of vitamin D insufficiency/deficiency in this study population (44%), PTH levels were mainly within the reference range." (PMID 36936151, 2023). "Vitamin D has an effect on fetal growth and development by regulating calcium homeostasis and parathyroid hormone levels, and vitamin D deficiency increases the risk of low birth weight infants." (PMID 38107136, 2023). "Data on serum levels of vitamin D, PTH, and related metabolites were obtained, and patients were stratified as having vitamin D deficiency or hyperparathyroidism according to standardized criteria." (PMID 36873448, 2023). "Older subjects with vitamin D deficiency have increased BMI, inflammation and PTH compared with those with insufficiency or optimal concentrations." (PMID 34991572, 2022). "Except for Vitamin D deficiency, daily calcium intake also affects the level of PTH; reduced intake of calcium is associated with high levels of serum PTH while excessive intake of calcium lowers PTH." (PMID 34435335, 2022). "The higher levels of PTH as a compensatory mechanism of vitamin D deficiency in diabetic patients can stimulate inflammatory cytokines like tumor necrosis factor (TNF)-α and interleukin (IL)-6 that have important roles in the pathogenesis of DR." (PMID 35778716, 2022).
vitamin D deficiency (continued). "Afterwards, biochemical workup showed severe HPH (calcium 15 mg/dl; PTH 898 pg/ml) and vitamin D deficiency (9.8 mg/dl)." (PMID 34626316, 2022). "Primarily, Vitamin D deficiency can cause secondary hyperparathyroidism, which leads to an increase of the serum parathyroid hormone (PTH) concentration." (PMID 34435335, 2022). "Meanwhile, patients with severe vitamin-D deficiency have very high levels of PTH in the presence of serum calcium levels in the upper range, and these levels were not been properly evaluated in order to rule out PHPT." (PMID 36143862, 2022). "Gender, sun exposure period, calorie intake, pigmentation phenotype, and PTH were found to be independent predictors of vitamin D deficiency." (PMID 36014846, 2022). "Low concentrations of 1, 25-dihydroxyvitamin D3 reduce phosphate absorption in the intestinal tract and promote secondary hyperparathyroidism, resulting in hyperphosphatemia, vitamin D deficiency, and increased parathyroid hormone levels." (PMID 35546659, 2022). "Vitamin D deficiency leads to an increase in PTH (parathyroid hormone) secretion, resulting in a continuous increase in intracellular calcium levels, which can lead to insulin resistance." (PMID 36079784, 2022). "Our study proposes to evaluate the prevalence of vitamin D deficiency in our setting according to season, sex, and age and to study the association with PTH levels." (PMID 37359435, 2022). "The risk of PMI in patients with IHD was 2.3 times higher than in non- IHD and increased to 3.1 in IHD patients with elevated PTH, to 3.9 in cases with vitamin D deficiency, to 4.4 if urea > 7.5 mmol/L, and to 4.5 if Urea/Albumin ratio ≥ 2.0." (PMID 36431261, 2022). "Vitamin D deficiency can cause secondary hyperparathyroidism and lead to an increase in the serum parathyroid hormone (PTH) concentration." (PMID 36583002, 2022). "In severe vitamin D deficiency (<10 ng/mL), PTH was higher than normal in 65% of patients, and ALP was high in 21% of the patients." (PMID 36428888, 2022). "While in our study we also find a positive correlation between BMI and preoperative PTH concentration, this can be explained by the vitamin D deficiency in patients with a high BMI, which will lead to an increase in PTH." (PMID 36268338, 2022). "Second, vitamin D deficiency triggers secondary hyperparathyroidism; parathyroid hormone (PTH) promotes myocytic hypertrophy and vascular remodeling." (PMID 34999719, 2022). "Intact parathyroid hormone (iPTH) level was markedly elevated in response to severe hypocalcaemia and vitamin D deficiency and that helped to exclude hypoparathyroidism." (PMID 35776989, 2022). "PTH level is thus elevated in vitamin D insufficiency, but when prolonged, can lead to progressive bone loss." (PMID 36356037, 2022). "In patients with mild vitamin D deficiency (15 to <20 ng/mL), PTH was high in 30%, and ALP was high in 13%." (PMID 36428888, 2022). "In 16.1% of those with CD and 12.7% of those with UC, the concentration of PTH was above normal, likely secondary to vitamin D deficiency." (PMID 35887903, 2022). "In patients with moderate vitamin D deficiency (10 to <15 ng/mL), PTH was high in 58% and ALP was high in 16%." (PMID 36428888, 2022). "For more than 40 years, vitamin D deficiency and the endocrine reaction with consecutive PTH overproduction has been taught to nephrology residents already early in their training." (PMID 35893866, 2022). "McKenna observed that during the winter, 40% of native young, healthy individuals in Central and Southern Europe suffered from vitamin D insufficiency, which was frequently associated with increased PTH levels." (PMID 35419240, 2022). "The resulting vitamin D deficiency reduces intestinal calcium absorption and CaSRs mediated PTH inhibition." (PMID 36015101, 2022).
vitamin D deficiency (continued). "The lack of iPTH suppression is attributed to high prevalence of vitamin D insufficiency at baseline and the supplementation regimen was inadequate to raise the 25(OH)D level to cause PTH suppression." (PMID 36356037, 2022). "The correlation analysis between vitamin D and PTH levels was also carried out, considering that even in situations of vitamin D deficiency, the active form [1,25(OH)2D] can present satisfactory levels under the mediation of PTH." (PMID 35919232, 2022). "Biochemical workup was consistent with hypercalcaemic primary hyperparathyroidism (HPH) (calcium 13.4 mg/dl, range: 8.5–10.5 mg/dl; PTH 667 pg/ml, range 12–88 pg/ml) and vitamin D deficiency (7.8 ng/ml)." (PMID 34626316, 2022). "There is an inverse association between PTH levels and vitamin D deficiency and up to a 20% decrease is expected with vitamin D supplementation in normal weight individuals." (PMID 35202418, 2022). "The reasons for elevated PTH in these 23 women were; Vitamin D insufficiency <50 nmol/L, vitamin D deficiency < 25 nmol/L, serum creatinine above 90 μmol/L, and severe liver cirrhosis." (PMID 34647149, 2022). "In those with mild, moderate, or severe vitamin D deficiency, PTH was higher than normal in 30%, 58%, and 65%, respectively." (PMID 36428888, 2022). "The indirect effects of Mg deficiency include decreased parathyroid hormone (PTH) secretion leading to vitamin D deficiency resulting in decreased bone formation." (PMID 36039217, 2022). "we also find a correlation between the concentration of vitamin D, PTH and bone manifestations, we note the presence of bone symptoms especially in patients with vitamin D deficiency (p: 0.04), and present high concentrations of PTH (p: 0.03)." (PMID 36268338, 2022). "In summary, in November 2011, vitamin D insufficiency associated with higher PTH and CTX values, and, in December 2018, all the BTMs (s-BSAP, P-OC, s-CTX, and U-NTX) values were increased." (PMID 34361096, 2021). "Either vitamin D deficiency or excess PTH was significantly associated with the prevalence of obesity, hypertension, or CKD, irrespective of diabetes status." (PMID 34531372, 2021). "The guideline was predominantly based on evidence on the prevention and management of vitamin D deficiency and the progressive increase of PTH." (PMID 33895867, 2021). "The prevalence of vitamin D deficiency and insufficiency increased over the two years and median serum 25(OH)D concentrations decreased, whereas serum PTH showed a trend of an increase." (PMID 34207469, 2021). "The observed joint association of vitamin D deficiency and PTH excess with incident diabetes remained significant and became even stronger in white women." (PMID 34531372, 2021). "From a pathophysiological point of view, prolonged vitamin D deficiency (perhaps exacerbated by calcium deficiency) decreases serum calcium with compensatory increases in serum PTH levels." (PMID 33553992, 2021). "Given its importance in calcium absorption and PTH interaction, some scholars assume that vitamin D deficiency is another potential risk factor of postoperative hypoparathyroidism." (PMID 34956363, 2021). "The results of this study suggest that a blunted PTH response to vitamin D deficiency is mainly observed in women with lower BMI, higher serum calcium levels, and higher 25(OH)D levels." (PMID 34580590, 2021). "The loss of renal function is frequently related to vitamin D deficiency and increased synthesis of PTH (secondary hyperparathyroidism)." (PMID 34867481, 2021). "Children were found to have low 25-hydroxyvitamin D, elevated parathyroid hormone, and elevated alkaline phosphatase levels, consistent with nutritional rickets secondary to vitamin D deficiency, calcium deficiency, or a combination of the two." (PMID 34097648, 2021). "Vitamin D deficiency leads to an increase in the PTH levels, which is further implicated in hastening the decline in mini-mental status scores." (PMID 33842148, 2021).
vitamin D deficiency (continued). "In individuals with normal renal function, the correction of vitamin D deficiency through cholecalciferol supplementation is sufficient to prevent the elevations in serum PTH." (PMID 34950686, 2021). "Vitamin D deficiency and increased concentration of PTH as well as calcium are implicated in the augmented risk of diabetes." (PMID 34950730, 2021). "Vitamin D deficiency, higher phosphate levels, and parathyroid hormone negatively affect muscle mass." (PMID 34785712, 2021). "Future studies should therefore interpret our results on vitamin D deficiency and PTH only as possible factors involved in the complexity of chronic pain." (PMID 34836290, 2021). "One study evaluating the effect of PTH levels on the risk of ONJ found that people with elevated PTH levels, which is directly associated with vitamin D deficiency, were more likely to experience osteonecrosis of the jaws than patients with increased PTH." (PMID 33800247, 2021). "Previously, vitamin D deficiency in HCV-infected patients was inversely correlated with elevated PTH serum levels." (PMID 33884041, 2021). "It is generally accepted that elevated PTH concentrations are an indicator of vitamin D deficiency; nevertheless, there are other factors that are involved in the physiological changes in PTH." (PMID 33504033, 2021). "Only vitamin D insufficiency was significantly associated with the postoperative PTH reduction ratio (OR = 2.2, p=0.017)." (PMID 34956363, 2021). "In all the preoperative and postoperative biochemical parameters, only preoperative PTH was significantly associated with vitamin D insufficiency (p = 0.038), which was in accordance with the inverse relationship of vitamin D and PTH." (PMID 34956363, 2021). "Women with vitamin D deficiency had significantly higher PTH concentrations compared to women with sufficient levels of vitamin D in both groups (p = 0.002 in early pregnancy and p = 0.001 in late pregnancy)." (PMID 33504033, 2021). "The increase in PTH can result from many factors, but the most important are vitamin D deficiency, renal failure, and age." (PMID 34768424, 2021). "In multivariate analysis, vitamin D insufficiency was significantly associated with the postoperative PTH reduction ratio ≥50% (OR = 2.2, p = 0.017)." (PMID 34956363, 2021). "Vitamin D deficiency offsets the influence of GFR on serum PTH in subjects with normal or near-normal renal function." (PMID 33995282, 2021). "From this point, PTH increases slowly with decreasing vitamin D and renal function, either alone or combined, until a vitamin D deficiency or CKD stage is reached." (PMID 33995282, 2021). "In the case of vitamin D deficiency or insufficiency, compensatory mechanisms will determine an increase in parathormone (PTH) levels in order to maintain calcium levels." (PMID 34065169, 2021). "We found one study reporting a decrease in PTH blood levels, calcaemia and urine calcium creatinine ratio in girls with low calcium intake and high prevalence of Vitamin D deficiency receiving a fortified milk compared to usual diet." (PMID 33499250, 2021). "One associated factor of vitamin D deficiency of this study was a high PTH level indicates that some critically ill patients had chronic vitamin D deficiency before ICU admission." (PMID 34966771, 2021). "This prospective population-based cohort study suggests a joint association of vitamin D deficiency and excess PTH with risk of developing diabetes among U.S. white postmenopausal women." (PMID 34531372, 2021). "In particular, vitamin D deficiency reduced the efficiency of intestinal calcium and reduced the absorption of phosphorus from dietary calcium and phosphorus, resulting in increased parathyroid hormone levels." (PMID 34833489, 2021). "Raised PTH levels which are usually regarded as one of the indicators of vitamin D deficiency are more frequently seen in Black individuals than in White individuals." (PMID 34783311, 2021).